NOD2 (nucleotide binding oligomerization domain containing 2)
Diseases named in the same sentence as NOD2 in open-access papers (continued):
Sharing a sentence is not in itself a finding about the gene and the disease.
tumor (continued). "NOD2 exerted its anti-tumor effect through activation of AMPK pathway, and the latter is recognized to be involved in regulating the response to chemotherapy; thus we were interested in defining whether NOD2 has any effect on the response of HCC cells to chemotherapy." (PMID 32144252, 2020). "In this study, we investigated the role of NOD2 in the pathogenesis of HCC and showed that NOD2 deficiency promoted hepatocarcinogenesis, while overexpression of NOD2 inhibited tumorigenesis and reversed resistance to chemotherapy, which indicated an anti-tumor effect of NOD2 on HCC." (PMID 32144252, 2020). "To determine whether NOD1 and/or NOD2 play a similar tumor suppressor role in an ER-negative breast cancer cell, we decided to overexpress these receptors in the highly invasive TNBC-derived Hs578T cell line in order to evaluate their impact in breast tumorigenesis in vitro." (PMID 30791886, 2019). "Therefore, we investigated whether NOD1 and/or NOD2 might act as a tumor suppressor in this cell model." (PMID 29615116, 2018). "However, the relationships between NOD2-mediated pyroptosis and tumor development remain unknown." (PMID 40761791, 2025). "Hence, the effectiveness of NOD2-dependent LY6Clo I-NCMs may be related to their ability to migrate into tumors in both the intra- and extravascular spaces, where they recruit NK cells that affect tumor lysis." (PMID 39545417, 2024). "After NLRP3-specific inhibitor MCC950 was added, the levels of NLRP3, ASC, NOD2 and AIM2 statistically decreased (p < 0.001 and p < 0.0001) upon stimulation with LPS and ATP of tumor cells." (PMID 39433537, 2024). "PTX treatment significantly increased inflammasome activation, as indicated by significantly increased NLRP3, ASC, NOD2 and AIM2 (p < 0.0001) expression in MDA-MB-231 tumor cells compared to control cells." (PMID 39433537, 2024). "QRT-PCR showed that the expression of AIM2, CASP4, GSDMB, NOD2, and RBCK1 was significantly upregulated in tumor samples." (PMID 36248876, 2022). "Compared with normal tissues, CASP6, GPX4, NOD2, and WNK1 were upregulated in HCC samples, presenting low- to medium-intensity expressions, and high expression of CYCS emerged in tumor tissues." (PMID 35368686, 2022). "Three genes (ELANE, NLRP7, and CASP5) were downregulated, whereas seven others (GSDMC, IL1A, NOD2, GZMB, GSDMA, IL1B, and PLCG1) were overrepresented in the tumour group." (PMID 35087586, 2022). "IHC staining validated that the protein levels of AIM2, CASP4, GSDMB, NOD2, and RBCK1 in tumor tissues were much higher than that in adjacent normal tissues." (PMID 36248876, 2022). "Then, we investigated the expression levels of AIM2, CASP4, GSDMB, NOD2, and RBCK1 in cell lines and tumor tissues by qRT-PCR, IHC." (PMID 36248876, 2022). "Our study shows that Gut-derived NOD2 agonist MDP could initiate nuclear autophagy and mediate lamin A/C degradation, which leads to nuclear matrix disruption, chromosomal aberration and accumulation of genomic mutations and instability, thereby promoting tumor formation." (PMID 33413510, 2021). "Using hepatic tumor cell lines, they further demonstrated that Nod2 binds to and activates AMPK signaling, which inhibits mTORC1 resulting in an anti-tumor effect." (PMID 33239685, 2020). "Immunization with MIS416, a novel adjuvant comprising NOD-2 and TLR9 stimulatory ligands, significantly prolonged survival in tumor-bearing mice." (PMID 25888637, 2015). "GMDP signals through NOD2 on myeloid cells to release IL-1b and NLRP3 to induce cytotoxic granzyme B+CD8+ T cells in the tumor and enhances the efficacy of anti–CTLA-4, anti–PD-1, and anti–PD-L1 in different mouse tumor models." (PMID 39895632, 2025). "Given the high expression of CCR2 and migration-related genes in NOD2-dependent LY6Clo I-NCMs, we hypothesized that signaling through CCL2/CCR2 plays a role in I-NCM–induced tumor regression." (PMID 39545417, 2024).
tumor (continued). "Collectively, our findings suggest that the induction of I-NCMs via NOD2 activation can attenuate tumor metastasis independent of conventional immune pathways necessary for immunotherapies." (PMID 39545417, 2024). "The PTX-increased expression of NOD2 suggests its anti-tumor activity and capacity to significantly increase the chemosensitivity of MDA-MB-231 cells to PTX, being able to increase the pyroptosis rate of tumor cells after treatment." (PMID 39433537, 2024). "NOD2 and RIPK2 were expressed differentially by tumor and normal or adjacent normal tissue." (PMID 38742117, 2024). "Compared with that of the negative control group, the tumor growth rate of the experimental group injected with NOD2 overexpression lentivirus was significantly inhibited." (PMID 36316517, 2023). "We conducted a subcutaneous tumorigenesis experiment in nude mice with OE33 cells, injected NOD2 overexpression lentivirus or negative control virus into the tumor tissue every week, measured the size of the tumor, and removed the tumor after three weeks." (PMID 36316517, 2023). "Furthermore, AIM2, CASP4, GSDMB, NOD2, and RBCK1 were also found to be highly expressed in ccRCC cell lines and tumor tissues, and GASP4 and GSDMB promote ccRCC cells’ proliferation, migration, and invasion." (PMID 36248876, 2022). "Moreover, the results from immunohistochemistry showed that there was the same immune‐positive signal for NOD2 and CD68, a macrophage marker molecule, in tumour tissues." (PMID 34268854, 2021). "Furthermore, according to the MTT assay, tumor cells with higher protein levels of NOD1, NOD2 and NF-κB had a relatively high growth rate." (PMID 32874130, 2020). "NOD2 is reported to activated NF-κB and MAPK pathways in macrophages and certain types of cancers, however in HCC cells, NOD2 mainly activated AMPK pathway and exerted its anti-tumor effect through AMPK pathway." (PMID 32144252, 2020). "Inducible LY6Clo CCR2-expressing NCMs could be expanded through the activation of NOD2 signaling to promote immunity against tumor metastasis independent of T and B lymphocytes." (PMID 39545417, 2024). "Furthermore, tumour tissues showed significantly decreased expression of cytoplasmic microbial sensors (NOD1 and NOD2) and downstream signaling molecules for innate microbial sensors such as CARD6, CARD9, and TRAF6 (p = 0.0207, p = 0.0040, and p = 0.0119, respectively)." (PMID 37007104, 2023). "Thus we identified NOD2 as a novel tumor suppressor and chemotherapeutic regulator in HCC cells for the first time, which indicated a potential therapeutic strategy for HCC by positive regulation of NOD2." (PMID 32144252, 2020). "Scatter plots of NOD1, NOD2, and NLRX1 mRNA expression level in the GEO database revealed that only NOD1 expression differed significantly between tumor and nontumor tissue (P = 0.007)." (PMID 28960882, 2017).
bacterial infection (83 papers, 2008 to 2026). "NOD2 plays a key role in the response against bacteria by recognizing the components of bacterial cell wall peptidoglycan, with NOD2 defects causing the onset or severity of bacterial infections in experimental animal models." (PMID 34573406, 2021). "While commonly associated with response to bacterial infection, NOD2 is increasingly recognized in response to both RNA and DNA viruses." (PMID 31235738, 2019). "In the current study it was found that the existence of the NOD2 variant R702W in the recipient is associated with an increased risk of bacterial infections after liver transplantation." (PMID 23977330, 2013). "We now show that the NOD2 R702W variant in the recipient is another innate risk factor for bacterial infections after OLT." (PMID 23977330, 2013). "The mutated NOD2 R702W genotype in the recipient is independently associated with an increased risk of bacterial infections after liver transplantation, indicating a predisposing role for this genetic factor impairing the recipient’s innate immune system." (PMID 23977330, 2013). "In conclusion, the mutated NOD2 R702W genotype in the recipient is associated with an increased risk of bacterial infections after liver transplantation." (PMID 23977330, 2013). "The current study adds to that knowledge by reporting the association of the NOD2 R702W variant in the recipient with increased risk of bacterial infections after liver transplantation." (PMID 23977330, 2013). "Previous reports have shown that Nod2 can protect cultured cells from bacterial infection and this activity is deficient in cells expressing the 3020insC polymorphism." (PMID 20531959, 2010). "Indeed, in mice deficient for XIAP, certain bacterial infections are unable to be cleared and cells are incapable of activating both the NOD2- and XIAP-mediated NF-κB survival pathways." (PMID 30389919, 2018). "Nod2-deficient mice exhibit reduced bactericidal activity, higher loads of commensal bacteria and increased susceptibility to colonization by pathogenic bacteria, and are, thus, prone to bacterial infections and intestinal inflammation." (PMID 27703457, 2016). "Indeed, NOD2 variants were shown to loose their ability to induce correct NF-κB activation and cytokines production in response to bacterial infection." (PMID 22815893, 2012). "Finally, very recent evidence suggests that NOD1 and NOD2 are essential for recruitment of ATG16L1 during bacterial infection, which is impaired in patients with CD-associated NOD mutants." (PMID 21209938, 2010). "NOD2 (nucleotide oligomerization domain 2) plays an important role in the host response to bacterial infection." (PMID 38343546, 2024). "NOD2 also interplays with TLRs during systemic bacterial infection to enhance immune response and promote immune responses after toleration by TLR ligands." (PMID 36193326, 2022). "RIPK2, also known as RIP2, is a protein used by NOD1 and NOD2 to direct the innate immune response against viral and bacterial infections." (PMID 36733771, 2022). "Dual oxidase 2 (DUOX2) protein during bacterial infection has been shown to be involved in NOD2-dependent ROS production." (PMID 36146565, 2022). "As receptors that recognize peptidoglycan fragments, NOD1 and NOD2 are known to be involved in the response to many bacterial infections." (PMID 36146565, 2022). "At present, this makes no sense from any existing perspective, since RIG1 should be either upregulated or downregulated by any viral infection, and NOD1 and NOD2 should be stimulated by the vast majority of bacterial infections." (PMID 33672738, 2021). "Just like other innate immunity genes, NOD2 is known for its role in natural host resistance to bacterial infection and therefore warrants investigation of its polymorphisms in association with MAP." (PMID 33644146, 2021). "In response to bacterial infection, CARD15/NOD2 acts as an intracellular bacterial receptor and activates the kappa B nuclear factor (NF-κB)." (PMID 34198814, 2021).
bacterial infection (continued). "Based on this and our study, it is possible that piscine BIRC2 is involved in the regulation of immune responses mediated by NOD1 and NOD2 signaling in response to bacterial infection." (PMID 34887869, 2021). "The NLRs, are intracellular innate immune molecules including NOD1/CARD4 and NOD2/CARD15 proteins that are essential for innate immune responses to bacterial infections and tissue injury." (PMID 32578848, 2020). "Travassos suggests that the sub-classes of the NLRs, NOD1, and NOD2 are essential for anti-bacterial infection by recruiting autophagy protein ATG16L1 to the plasma membrane at the bacterial entry site." (PMID 33013364, 2020). "Another study observed that NOD2 is critical for resistance to bacterial infection via expression of intestinal anti-microbial peptides named cryptdins." (PMID 32774333, 2020). "The presence of NOD2 close to the cell surface is important for the early response after bacterial infection and the EMMPRIN-NOD2 complex seems to be involved in innate immune responses." (PMID 29419744, 2018). "We next examined the physiological relevance of ZNRF4-mediated RIP2 regulation during NOD2-tolerant conditions in the context of bacterial infection." (PMID 28656966, 2017). "NOD2 also plays a specific protective role against intracellular bacterial infection in the intestine (e.g., Listeria Monocytogenes)." (PMID 28165033, 2017). "Optimal regulation of the innate immune receptor nucleotide-binding oligomerization domain-containing protein 2 (NOD2) is essential for controlling bacterial infections and inflammatory disorders." (PMID 28656966, 2017). "Through the innate immune system, NOD2 provides a defensive strategy to protect the hosts against bacterial infection." (PMID 27703457, 2016). "Nucleotide-binding oligomerization domain-containing protein 2 (NOD2) is an intracellular, cytoplasmic sensor of bacterial infection, specifically binding muramyl dipeptide (MDP) on bacterial peptidoglycans." (PMID 27486774, 2016). "The pattern recognition receptors NOD1 and NOD2 play an important role in the pro-inflammatory immune response to bacterial infections." (PMID 24960071, 2014). "With respect to bacterial infection, NOD2-mediated peptidoglycan sensing regulates mononuclear cell recruitment and chemokine production, which promotes clearance of Streptococcus pneumonia." (PMID 23675299, 2013). "The possibility of a role for NOD2 in non-bacterial infections has also been suggested, with NOD2 having been shown to induce an IFNβ-driven antiviral response following recognition of single-stranded viral RNA." (PMID 24137163, 2013). "Nevertheless, increasing numbers of recent reports suggest that NOD1 and NOD2 have important functions in non-bacterial infections." (PMID 23162548, 2012). "It has been previously shown that IL-23 has an important role in bacterial infections and NOD2 activation seems to be highly responsible for DC elevated IL-23 production." (PMID 22984550, 2012). "It recognizes muramyl dipeptide and simulates a bacterial infection by binding to NOD2 (NOD2 is a pattern recognition receptor which is found in several kinds of white blood cells, mainly monocytes and macrophages) activating white cells." (PMID 23316341, 2012). "The NOD2/CARD15 protein, restricted to intestinal epithelial cells and monocyte/macrophage lineage, plays a role in the innate immune response to bacterial infections in the gastrointestinal tract." (PMID 23091728, 2012). "Th17 responses are important for clearance of bacterial infections and are initiated after activation of the intracellular pattern recognition receptors NOD2 or dectin-1." (PMID 19834553, 2009). "Different than TLR2 and NOD2, IFN-γ is a cytokine responsible for a wide array of immune functions, primarily related to activation of type 1 immunity, which is associated with cell-mediated defense against viral and bacterial infections." (PMID 41369133, 2025).
bacterial infection (continued). "Furthermore, genomic-wide association studies (GWASs) have found a link between CD and the expression of nucleotide oligomerization domain 2 (NOD-2), a key player in the innate immune response to bacterial infection and mucosal inflammation." (PMID 38732603, 2024). "Autophagy is induced when S. aureus activates pattern recognition receptors (PRRs) such as toll-like receptor 2 (TLR2) and nucleotide-binding oligomerization domain-containing protein 2 (NOD2), and is considered as a defense mechanism against bacterial infection." (PMID 39310788, 2024). "NOD2-deficient mice display increased susceptibility to bacterial infection while spontaneous intestinal inflammation is consistently absent in NOD2-/- mice or knock-in mice." (PMID 37869013, 2023). "The recruitment of NOD2 to Rac-induced dynamic cytoskeletal structures could be a strategy to both repress NOD2-dependent NF-kB signaling in unstimulated cells and rapidly mobilize NOD2 during bacterial infection." (PMID 34898657, 2021). "Furthermore, NOD2 and NOD1 receptors can recruit ATG16L1 proteins upon bacterial infection to activate autophagy, while the A allele of rs2241880 impairs the activation of autophagy to increase the risk of septic shock in VAP patients." (PMID 32940422, 2020). "Consequently, Nod2 agonist MDP can be used as B cell adjuvant to protect from fast-replicating bacterial infection through enhancing direct B cell activation and IgG2b production independent of T cells and BCR stimulation." (PMID 31886297, 2019). "Recently, the role of NOD2 protein in bacterial infection has attracted increasing attention." (PMID 30186539, 2018). "Importantly, Nod2 is one member of important microbial sensors, which promotes pro-inflammatory signaling and cytokine networks to fight off bacterial infections." (PMID 29552291, 2018). "Interestingly, it is well recognized that NOD2 is involved in host defense against bacterial infections and various inflammatory diseases." (PMID 28068976, 2017). "NOD2 is a kind of cytosolic proteins that respond to intracellular fragments of bacterial peptidoglycan, which is also crucial for innate immune responses to certain bacterial infections." (PMID 28693414, 2017). "However, NOD2-tolerized Znrf4 knockdown macrophages showed significantly enhanced ability to control bacterial infection." (PMID 28656966, 2017). "Thus, we propose that NOD2 has both protective and provocative functions in immunity to bacterial infection." (PMID 23675299, 2013). "Moreover, the use of Nod1−/− and Nod2−/− mice supported the key role of these molecules in restricting bacterial infection." (PMID 23162548, 2012). "Additionally, XIAP promoted maximal production of pro-inflammatory cytokines upon bacterial infection in vitro or in vivo, or in response to combined treatment with NOD2 and TLR2 ligands." (PMID 18769721, 2008). "Activation of either NOD1 or NOD2 activates TAK1, leading us to hypothesize that during bacterial infection, XIAP may facilitate this key association, linking cytosolic sensors to downstream signaling mediators." (PMID 18769721, 2008). "While the effect of NOD2 genotype-related dysregulation of cytokine production may not be the only contributing pathway to the cytokine storm, the role of NOD2 and other sensors of bacterial infection has long been proposed as major factors in GvHD responses." (PMID 23119165, 2012). "NOD1 and NOD2, founding members of the NOD-like receptor (NLR) family, play a crucial role in host defense against bacterial infections." (PMID 42213708, 2026). "RIP2 is a pivotal regulator of inflammatory responses to bacterial infections, where it is activated by the NOD1 and NOD2." (PMID 38012669, 2023). "It is published before the NOD1 and NOD2 and their adaptor serine-threonine kinase RICK: kinase (Rip2) were related to immune responses induced by bacterial infection." (PMID 34812410, 2021).